FYN (FYN proto-oncogene, Src family tyrosine kinase)
Diseases named in the same sentence as FYN in open-access papers (continued):
Sharing a sentence is not in itself a finding about the gene and the disease.
gastric cancer (7 papers, 2021 to 2025). A primary or metastatic malignant neoplasm involving the stomach. "For instance, in gastric cancer, FYN directly interacts with TOPK in gastric cancer cells, leading to the phosphorylation of TOPK at Y272 and subsequent increases in cell proliferation and metastasis." (PMID 40826334, 2025). "At this stage, we have revealed that FYN in gastric cancer promotes proliferation and metastasis through phosphorylation of TOPK to enhance its oncogenic activity and activation of TOPK downstream proliferation and metastasis-related signaling pathways." (PMID 36740671, 2023). "FYN has been demonstrated to promote gastric cancer metastasis by activating STAT3-mediated epithelial-mesenchymal transition." (PMID 36740671, 2023). "Additionally, the reduction in FYN expression also significantly inhibited gastric cancer cell migration and invasion." (PMID 37016377, 2023). "In gastric cancer, FYN was overexpressed and positively correlated with metastasis." (PMID 36498797, 2022). "Similar to SRC, FYN is an SFK that is overexpressed in GC and is positively correlated with metastasis and may promote gastric cancer metastasis by activating STAT3-mediated epithelial-mesenchymal transition." (PMID 33479376, 2021). "However, the mechanisms that FYN promotes gastric cancer (GC) progression remain largely unknown." (PMID 37016377, 2023). "Moreover, silencing of FYN in gastric cancer cells significantly inhibited cell proliferation, migration and invasion, and nude mice tumorigenic and metastatic models also confirmed that FYN could promote GC proliferation and metastasis." (PMID 37016377, 2023).
chronic myeloid leukemia (6 papers, 2016 to 2024). "In chronic granulocytic leukemia, increased FYN expression and activity promote the transition from chronic granulocytic leukemia to the acute phase and accelerate cell proliferation." (PMID 36740671, 2023). "Increased FYN expression and activity in chronic granulocytic leukemia enhances the transition into the acute period and stimulates cell growth." (PMID 37324495, 2023). "In chronic myeloid leukemia (CML) FYN expression was upregulated and depletion of FYN was associated with increased sensitivity to imatinib as well as decreased cell growth and colony formation." (PMID 26848862, 2016).
glioblastoma (6 papers, 2016 to 2025). The most malignant astrocytic tumor (WHO grade IV). "In glioblastoma, FYN phosphorylates PIKE-A, increasing its binding to AMPK, lowering AMPK’s tumor suppressive function, and stimulating tumor cell growth." (PMID 37324495, 2023). "Expressing constitutively active EGFR mutant EGFRvIII results in FYN phosphorylation, which promotes glioblastoma progression and invasion." (PMID 36740671, 2023). "In glioblastoma, FYN phosphorylates PIKE-A and thus promotes its binding to AMPK, inhibits the tumor suppressive effect of AMPK, and promotes tumor cell proliferation." (PMID 36740671, 2023). "Glioblastoma research has revealed that PIKE-A impairs the tumor suppressive actions of AMPK, which are mediated by FYN." (PMID 36498797, 2022).
lymphoma (6 papers, 2019 to 2024). A malignant (clonal) proliferation of B- lymphocytes or T- lymphocytes which involves the lymph nodes, bone marrow and/or extranodal sites. "In AITL lymphoma, multiple mutations in FYN have been detected, which invalidate the inhibitory function of the FYN domain SH2, resulting in a constitutive activation of the tyrosine kinase and T-cell activation." (PMID 32796826, 2020). "In acute lymphoma, FYN interacts with FLT3-ITD to selectively activate STAT5 and induce the transformation of lymphoma cells, and inhibition of FYN may assist in treating patients with acute lymphoma." (PMID 36740671, 2023). "The heterogeneous expression of FYN is also reported to have prognostic implications in lymphoma." (PMID 35453806, 2022). "In addition to frequent somatic mutations in RHOA and epigenetic modifiers, several studies have shown frequent alterations affecting TCR signaling-related genes, including CD28, FYN, PLCγ1 and VAV1 in cutaneous T-cell lymphomas, AITL and adult T cell leukemia/lymphoma." (PMID 30814910, 2019).
neuroblastoma (6 papers, 2015 to 2023). Neuroblastoma (NB) is the most common solid, extracranial childhood tumor. "In advanced neuroblastoma, FYN levels are downregulated and positively correlate with survival in patients with advanced neuroblastoma." (PMID 36740671, 2023). "Analysis of mRNA expression across the CCLE lines revealed that FYN was expressed at higher levels in the cell lines derived from the tumors such as neuroblastoma, small cell lung cancer, and medulloblastoma." (PMID 26624980, 2015). "In addition, it has been demonstrated that high expression of activated FYN induces differentiation and growth arrest in neuroblastoma cells, yet patients with neuroblastoma with high expression of FYN have long-term survival." (PMID 37016377, 2023). "This is consistent with previous work showing that FYN and LYN show different responses in activity, association with the scaffold protein PAG1, and intracellular localization when activated by different RTKs in neuroblastoma cells." (PMID 36996232, 2023). "As for FYN, its increased expression correlated with shorter failure-free survival in Hodgkin lymphoma, but downregulation of its activity correlated with disease progression in neuroblastoma." (PMID 29937990, 2018).
Sepsis (6 papers, 2020 to 2024). Sepsis is defined as life-threatening organ dysfunction caused by a dysregulated host response to infection. "Similarly, FYN, known for its role in T-cell signaling and immune responses, has been implicated in other pathological conditions, but its specific role in sepsis has been less clear." (PMID 39430765, 2024). "In conclusion, our comprehensive analysis identifies FCER1G and FYN as promising biomarkers for sepsis, providing valuable insights into the molecular mechanisms of this complex condition." (PMID 39430765, 2024). "Our study’s insights into FCER1G and FYN enhance our understanding of sepsis and open new avenues for diagnostics and therapeutics." (PMID 39430765, 2024). "FCER1G expression was found to be elevated in sepsis patients, while FYN expression was reduced, consistent with findings from the training set." (PMID 39430765, 2024). "The qRT-PCR results showed that FYN was downregulated in the sepsis patient group compared to the healthy control group, while FCER1G was upregulated in the sepsis patient group compared to the healthy control group." (PMID 39430765, 2024). "Microarray analysis has indicated abnormalities in the expression of immune-related genes in children with sepsis, including FYN, FBL, ATM, WDR75, FOXO1, and ITK." (PMID 36855207, 2023). "In our study, the expression of LCK and FYN was decreased in patients with sepsis, indicating possible suppression of T-cells and NK cells, as well as a role for these proteins in platelet functions during sepsis, which warrants further exploration." (PMID 33132754, 2020). "Additionally, experimental studies are needed to fully understand the mechanisms by which FCER1G and FYN influence sepsis progression." (PMID 39430765, 2024). "Currently, there are many biomarkers used in the prediction of sepsis prognosis, such as CD247, FYN, CD96, etc., most of which have been studied individually as single biomarkers." (PMID 38755528, 2024). "Patients with sepsis exhibit higher expression of FCER1G and lower expression of FYN, suggesting a complex interplay between these genes in the immune response during sepsis." (PMID 39430765, 2024). "In conclusion, our study illuminates the complex genetic landscape of sepsis, with a particular focus on the roles of FCER1G and FYN." (PMID 39430765, 2024). "Our findings revealed significant alterations in the expression of several coagulation-related genes in sepsis patients, with FCER1G and FYN emerging as potential biomarkers." (PMID 39430765, 2024). "Through searching the sepsis-related publication of the key genes, CCR7, CXCR3, FYN, CEACAM1, CD81, AMPH, HLA-DMA, and G protein-coupled receptors (GPR18) were considered to be key genes." (PMID 34484417, 2021). "However, the roles of LCK and FYN in sepsis have not been entirely elucidated." (PMID 33132754, 2020). "The upregulation of FcγR‐related genes, such as FCGR3A, FCGR1A, LYN, SYK, FYN and SRC, was detected in the prefrontal cortex, hippocampus, heart and colon of our sepsis patients, but not in the kidneys or lungs." (PMID 37731199, 2023).
colon cancer (5 papers, 2020 to 2023). "FYN interacts with ARHGEF16 to regulate the proliferation and migration of colon cancer cells, and knockdown of FYN expression decreases ARHGEF16 protein levels in colon cancer cells." (PMID 36740671, 2023). "We also showed that ARHGEF16-induced colon cancer cell proliferation and migration were tightly dependent on FYN." (PMID 32811808, 2020). "In summary, our findings suggest that ARHGEF16 contributes to the proliferative ability of colon cancer cells through FYN." (PMID 32811808, 2020). "Taken together, these results indicate that the FYN-ARHGEF16 axis plays crucial roles in promoting colon cancer cell proliferation and migration." (PMID 32811808, 2020). "We further validated that ARHGEF16 promoted proliferation and migration in colon cancer cells, which were strongly dependent on FYN." (PMID 32811808, 2020). "FYN interacts with ARHGEF16 to promote colon cancer cell proliferation." (PMID 36740671, 2023). "The next study confirmed that FYN promotes metastatic invasion in colon cancer." (PMID 36740671, 2023). "Moreover, cell migration was also inhibited in ARHGEF16 + Sh-FYN HCT116 cells relative to ARHGEF16 + Sh-control HCT116 cells, suggesting that FYN is required for ARHGEF16-induced colon cancer cell migration." (PMID 32811808, 2020). "Our results suggested that FYN-ARHGEF16 signaling could serve as a novel molecular target for developing anti-colon cancer therapies." (PMID 32811808, 2020). "Knocking down FYN expression decreased ARHGEF16 protein level in colon cancer cells." (PMID 32811808, 2020). "However, what is exactly FYN functions in colon cancer, including whether it works directly with ARHGEF16 to perform an oncogenic function or plays a role in tumorigenesis associated with this oncogenic function, remains unknown." (PMID 32811808, 2020). "Thus, co-targeting ARHGEF16 and FYN maybe a relatively effective approach for anti-colon cancer therapy, as these molecules are highly active in and related to colon cancer." (PMID 32811808, 2020). "Our studies detailed below investigated the roles of FYN and ARHGEF16 and their relationship in colon cancer through in vitro experiments." (PMID 32811808, 2020). "We further demonstrated that ARHGEF16-induced colon cancer cell proliferation and migration were dependent on FYN since knockdown FYN abolished the ARHGEF16-induced proliferation and migration of colon cancer cells." (PMID 32811808, 2020). "The FYN-ARHGEF16 axis mediates colon cancer progression and is a potential therapeutic target for colon cancer treatment." (PMID 32811808, 2020). "FYN and ARHGEF16 interact to promote the migration of colon cancer cells." (PMID 36740671, 2023).
liver cancer (5 papers, 2022 to 2025). An epithelial or non-epithelial malignant neoplasm that arises from the liver. "In our research, PA2G4 was found to promote EMT of liver cancer cells by stabilizing mRNA of FYN in a YTHDF2 dependent manner, and was an independent risk factor for recurrence." (PMID 35526051, 2022). "As one of the Src family proteins and tumor suppressor genes, FYN has been little researched on liver cancer." (PMID 35397600, 2022). "Since the FYN gene is rarely studied in HCC, we will do further researched on FYN to clarify its role in liver cancer progression." (PMID 35397600, 2022). "Therefore, we explored the biological functions of FYN in liver cancer cells." (PMID 35397600, 2022). "The results demonstrated that the expression of FCER1G, PFN1, ACTG1, PABPC1, CALM1, and RPS8 was significantly upregulated in the liver cancer cells, whereas KLRB1, LDB2, and FYN exhibited the opposite trend." (PMID 37397471, 2023).
COVID-19 (4 papers, 2022 to 2025). A disease caused by infection with severe acute respiratory syndrome coronavirus 2. "By 6 weeks post-inclusion, COVID-19 hypermethylation of genes with the highest fold-change compared to healthy controls included FAM178B, FYN, TMCC1, TMEM212-AS1, and FIG4, while the top five hypomethylated genes were GIT2, PDGFRB, SEMA6D, TNFAIP8, and ETV6." (PMID 41227320, 2025). "Several kinases, such as NTRK1 (10,495th → 29th), FYN (3902nd → 46th), ABL1 (7261st → 91st), and SRC (8965th → 56th), are being studied for repurposing several kinase inhibitors for COVID-19 treatment." (PMID 36291657, 2022).
diabetes (4 papers, 2017 to 2025). "SRC/EGFR/FYN, on the other hand, provides some therapeutic leverage, but it more specifically addresses diabetes-related complications." (PMID 41011980, 2025). "In the context of diabetes pathogenesis, SRC, FYN, and EGFR are significantly implicated in the development of vascular complications, such as diabetic kidney injury, and have been reported to prevent/improve diabetic nephropathy and other diabetic-related kidney injuries." (PMID 41011980, 2025).
Obesity (4 papers, 2017 to 2025). Accumulation of substantial excess body fat. "Studies have shown that the fat mass and obesity‐associated protein reduces the m6A modification level of Src family tyrosine kinase (FYN) mRNA, thereby inhibiting FYN expression." (PMID 40821693, 2025). "FYN, another pivotal protein, promotes lipid utilization and energy expenditure in knockout mice, elevating fatty acid oxidation in skeletal muscle and adipose tissue while mitigating obesity associated with AMPK activation." (PMID 40244284, 2025).
ovarian carcinoma (4 papers, 2020 to 2025). A malignant neoplasm originating from the surface ovarian epithelium. "Indeed, a recent report suggested that higher levels of FYN protein are associated with chemo-resistance in ovarian cancer patients and that depletion of FYN significantly resensitizes ovarian cancer cells to platinum-based chemotherapy." (PMID 40296913, 2025). "Among ovarian cancer patients, FYN is one of the indispensable kinase targets of CXC chemokines, which activate the downstream signaling pathways to influence tumor progression." (PMID 36091768, 2022). "Oncoprint profile of CYCS, VEGFA, IL6, UQCRC1, UQCRFS1, COX5B, ACKR3/CXCR7, and FYN indicated that these genes were either amplified or overexpressed in 4–25% of the ovarian cancer patients." (PMID 34439877, 2021). "The identification of CYCS, VEGFA, IL6, UQCRC1, UQCRFS1, COX5B, ACKR3/CXCR7, and FYN as pro-tumorigenic nodes designates them as the novel and potentially druggable targets for effective targeted adjuvant therapy for ovarian cancer." (PMID 34439877, 2021).
Parkinson disease (4 papers, 2013 to 2025). A progressive degenerative disorder of the central nervous system characterized by loss of dopamine producing neurons in the substantia nigra and the presence of Lewy bodies in the substantia nigra and locus coeruleus. "The analysis of genes involved in the selected DAVID/IPA pathways revealed more genes related to Parkinson's disease manifestation, such as FYN (protein-tyrosine kinase oncogene belonging to focal adhesion pathway) and VEGF (from VEGF signaling pathway)." (PMID 24688734, 2013). "FYN-mediated signaling, activates phosphorylation of alpha-synuclein, and the accumulation of this phosphorylated protein in the brainstems of patients with Parkinson's disease is a signature mark of this disease." (PMID 24688734, 2013). "FYN can activate NLRP3 inflammatory vesicles and amplify inflammation in Parkinson’s disease." (PMID 40958910, 2025).
schizophrenia (4 papers, 2010 to 2024). A major psychotic disorder characterized by abnormalities in the perception or expression of reality. "Results show that FYN, which the researcher had not previously considered to be relevant, interacts with genes in both lists and was reported to be related to schizophrenia." (PMID 21143788, 2010).
squamous cell carcinoma (4 papers, 2007 to 2025). A carcinoma arising from squamous epithelial cells. "Moreover, VAV1 was discovered when DNA from five esophageal carcinomas were tested for their transforming activity, which is compatible with the fact that FYN is implicated in squamous cell carcinoma." (PMID 17868464, 2007).
acute lymphoblastic leukemia (3 papers, 2023 to 2024). Leukemia with an acute onset, characterized by the presence of lymphoblasts in the bone marrow and the peripheral blood. "Phosphorylated FYN (pTyr530) is upregulated in Integrin α6-deficient acute lymphoblastic leukemia (ALL) and mediates the development of chemoresistance through adhesion." (PMID 36740671, 2023). "In Acute lymphoblastic leukemias, FYN is a target gene for the transcription factor RUNX2." (PMID 36740671, 2023). "Kinase profiling revealed that GNF-7 not only evidently inhibited LYN, FYN, SRC, YES, BTK and CSK kinase that can also inhibited by dasatinib, but also inhibited ACK1 and mitogen-activated protein kinase (GCK) to kill NRAS-dependent cells in AML and acute lymphoblastic leukemia." (PMID 38037057, 2023).
colorectal cancer (3 papers, 2021 to 2025). A primary or metastatic malignant neoplasm that affects the colon or rectum. "Similarly, ZAP70, PTPRC, FYN and WASP2 were found to be dysregulated in different cancers including breast, leukemia, colorectal cancer, etc.." (PMID 34834481, 2021).
leukemia (3 papers, 2021 to 2023). A malignant (clonal) hematologic disorder, involving hematopoietic stem cells and characterized by the presence of primitive or atypical myeloid or lymphoid cells in the bone marrow and the blood. "FYN is a major downstream target of ABL1 in human leukemias and LYN signaling promotes resistance to ABL1 inhibitors." (PMID 38047771, 2023).
renal carcinoma (3 papers, 2018 to 2022). A carcinoma arising from the epithelium of the renal parenchyma or the renal pelvis. "Src kinase signaling members were also predominant in the core, including SRC, LCK, LYN, FYN and PTPN6, among which LYN has been causally implicated in renal cancer." (PMID 29861861, 2018). "Interestingly, FYN, LRSAM1, IL20RB, CXCL11, S100A1, and MAP3K14 are also well-recognized biomarkers in the prognosis of renal cancer, which is reminiscent of the pancreatic metastasis from renal cell carcinoma in some earlier studies." (PMID 36428747, 2022).
sarcoma (3 papers, 2012 to 2025). A usually aggressive malignant neoplasm of the soft tissue or bone. "To examine the clinical relevance of this finding, we analyzed FYN expression in sarcoma patients and found that FYN mRNA levels are significantly lower in synovial sarcoma than in any type of sarcomas that do not carry the SS18-SSX fusion." (PMID 39045458, 2024). "Analysis using the U133Plus gene expressions expands this result by including JUN (JUN oncogene), MAPK8 (mitogen activated protein kinase 8), SRC (v-SRC sarcoma) and FYN (FYN oncogene related to SRC) as protein kinases within dasatinib’s discriminating genes." (PMID 23056181, 2012). "BK40196 is a dual c-KIT/c-Abl (Abelson) inhibitor but also displays binding affinity to other kinases, including fused in sarcoma (SRC) and FYN." (PMID 40137158, 2025).
acute myeloid leukemia (2 papers, 2016 to 2023). Acute myeloid leukemia (AML) is a group of neoplasms arising from precursor cells committed to the myeloid cell-line differentiation. "FYN expression is dysregulated in acute myeloid leukemia (AML) patient samples, and FYN is associated with wild-type FLT3 and oncogenic FLT3-ITD." (PMID 36740671, 2023). "In this report, we have studied the role of FYN in FLT3 signaling in respect to acute myeloid leukemia (AML)." (PMID 26848862, 2016).